GSK3B (glycogen synthase kinase 3 beta)
Diseases named in the same sentence as GSK3B in open-access papers (continued):
Sharing a sentence is not in itself a finding about the gene and the disease.
infection (continued). "Mice were sacrificed 3 weeks after infection and Gsk3β expression was evaluated by immunofluorescent staining of brain slices using two different antibodies." (PMID 29706865, 2018). "Higher expression of SIRT2 leads to activation of AKT/GSK3β/β catenin signalling pathway during the infection." (PMID 30452468, 2018). "Phosphorylated GSK3β was markedly increased according to inhibition of PLC in LPC-treated cells during H37Ra infection." (PMID 29755479, 2018). "As expected, an infection of Mtb H37Rv activated Akt and GSK3β, the downstream signaling of the PI3K pathway." (PMID 30356420, 2018). "Data in this work indicate that the relative abundance of phospho-GSK3α was higher than that of phospho-GSK3β during the infection of BEC with viable S. aureus, as we have previously reported." (PMID 29434603, 2018). "GSK3β protein levels did not change significantly; however, enzyme activity appeared to be modulated by HSV-1 infection, which continued until phosphorylation inactivated GSK3β in the later stages of infection." (PMID 29559905, 2018). "At initial stages of infection, a gradually decreasing fraction of GSK3α and in minor proportion GSK3β remains activated, implying an indirect correlation between the amount of GSK3α in its active form and the expression of IL-8." (PMID 29434603, 2018). "SV-HUC-1 cells were transfected with GSK3β overexpression lentiviral vector at multiplicity of infection (MOI) of 5, 10, 15, 30 and 50 for 72 h." (PMID 28981096, 2017). "HCjE cells responded to Ct infection by augmented GSK3β-inhibitory phosphorylation and activation of PI3K/AKT, suggesting involvement of Wnt and integrin signaling." (PMID 28660176, 2017). "We examined the level of phosphorylated GSK3β in P. gingivalis-infected OECs at 72, 96, and 120 h-post-infection, and compared them with uninfected OECs." (PMID 29250491, 2017). "Upon the infection of Ad5-AlncRNA, the phosphorylation of mTOR, GSK3β, S6K and 4EBP1 was reduced, sequentially p27 expression was increased while cyclin D1 expression was reduced." (PMID 27689326, 2016). "Upon infection with viral DNA or RNA, TRIM9 short isoform undergoes Lys-63-linked auto-polyubiquitination and recruits GSK3β to TBK1, resulting in the activation of the IRF3 signaling pathway." (PMID 27667714, 2016). "The phosphorylation of two peptides in the canonical Wnt pathway was significantly altered at the 4 days after Salmonella-infection time point: glycogen synthase kinase 3β (GSK-3β) and β-catenin." (PMID 26664962, 2015). "IAV-infection-induced β-catenin degradation was significantly inhibited in GSK-3β-knockdown cells, and transfection of cells with recombinant β-catenin significantly suppressed IAV-induced hyperpermeability." (PMID 25385175, 2015). "Within 30 min after infection with S. Enteritidis, heterophils had a significant (p ≤ 0.05) decrease in total GSK-3β." (PMID 26664916, 2014). "The increased transcription of GSK-3β in heterophils during their interaction with S. Enteritidis implicates its physiological role in the activation of the pro-inflammatory response to infection." (PMID 26664916, 2014). "Concentrating on the canonical GSK-3 pathway from the chicken whole genome array, we found a significant upregulation in the expression of Axin-1, GSK-3β, and β-catenin in the heterophils 30–60 min after infection with S. Enteritidis." (PMID 26664916, 2014). "First, we confirmed that infection of S. Enteritidis by the heterophils induced the phosphorylation of GSK-3β at Ser9." (PMID 26664916, 2014). "In summary, we have demonstrated a role for GSK-3β in mediating a pro-inflammatory response in chicken heterophils to infection with S. Enteritidis." (PMID 26664916, 2014). "S. Enteritidis interaction with heterophils alters GSK-3β activity by stimulating phosphorylation at Ser9 and that peaks by 30 min post-infection." (PMID 26664916, 2014).
infection (continued). "Next, TEER measurements (shown at 18 hr post infection) were performed on BMVEC expressing the mutants of GSK3β protein." (PMID 23418486, 2013). "Apart from encoding the GSK3β mutant, these bicistronic vectors also express GFP, thus providing visualization of an infection efficiency of ∼80%." (PMID 23418486, 2013). "Among such regulating kinases, DNA-PK, Chk2, JNK1 and Gsk3β genes are all under-expressed following infection." (PMID 21651802, 2011). "GSK-3β and proton pump were investigated by western blotting after up-regulating Akt expression by Ad-Akt infection." (PMID 21439087, 2011). "Increasing levels of phosphorylated ERK, Akt and GSK3β were detected from 24–96 hours post-infection, concomitant with RV-induced apoptotic signals." (PMID 15631631, 2005). "Mechanistically, early infection transiently activated NRF2 via AKT-dependent inhibition of GSK3β, enhancing antioxidant defenses, but prolonged infection suppressed NRF2 activity due to AKT dephosphorylation and GSK3β activation, sustaining NOX4 upregulation and exacerbating oxidative stress." (PMID 41504438, 2026). "Notably, Yersinia stimulates the phosphorylation of GSK-3β during the early stages of macrophage infection." (PMID 41413615, 2025). "Therefore, we investigated the phosphorylation status of GSK-3β following infection of CEF cells with different strains of MDV." (PMID 38638910, 2024). "In conclusion, infection of SARS-CoV-2 in TPH2-positive cells of the brain VTA may result in increased phosphorylation of tau through activation of GSK3β, induction of neuronal cell death, suppression of TPH2 expression, and decreased serotonin synthesis." (PMID 39475992, 2024). "In the absence of infection and in the case of E. piscicida infection, CD44a deficiency decreased the levels of phosphorylated and total proteins of Akt and GSK3β." (PMID 36042265, 2022). "Additionally, five genes that seem to facilitate infection of the SARS-CoV2 virus are glycogen synthase kinase 3 beta (GSK-3β), furin protease, TMPRSS2, a disintegrin and metalloprotease 17 (ADAM17), and neuropilin-1." (PMID 35444632, 2022). "However, the opposite trend was observed in HPSE knockout cells where the expression level of p-GSK-3β (Ser9) was reduced following infection." (PMID 34749529, 2021). "Finally, data discussed in this review indicate that inhibition of GSK3β can induce a proinflammatory or anti-inflammatory response during infection, depending mainly on the microbial stimulus." (PMID 34017345, 2021). "Recently, studies conducted in Huh7.5 cells using a HCVreplicon showed that treatment with a GSK3β inhibitor affected viral replicationcycle late during infection, very likely at the assembly and release of viralparticles,8) which was confirmed by the findings in the current study." (PMID 32130369, 2020). "The result was that the level of GSK3β increased 36 h after BPIV3 infection." (PMID 32127006, 2020). "Based on this work andour findings, we presume that activation of PI3K/Akt pathway and subsequentphosphorylation of GSK3β as early as 1 min post-infection occur upon virus bindingto the cell receptor involved in activation of the pathway even before viralendocytosis begins." (PMID 32130369, 2020). "However, compelling evidence, including ours, demonstrated that the virus promotes GSK3β activation and tau hyperphosphorylation in in vitro and in vivo models of infection." (PMID 32610629, 2020). "Together, it can be assured that degradation of β-catenin via GSK3β occurred after BPIV3 infection." (PMID 32127006, 2020). "The result showed that the expression of GSK3β was up-regulated post-infection." (PMID 32127006, 2020).
infection (continued). "DENV-2 induces inhibitory phosphorylation of GSK3β (Ser9) in Huh7cells - To assess changes to GSK3β activities during infection withDENV-2, we performed dose dependent infection experiments for up to 2 h andevaluated GSK3β phosphorylation status in situ using In-CellWestern." (PMID 32130369, 2020). "Importantly, we compared GSK3β activation duringthe stages of infection and assessed its influence on cellular responses and viralrelease." (PMID 32130369, 2020). "Further understanding of how the kinase activity of GSK3β is a crux for infection may lead to the development of therapeutics that act on cellular signaling pathways and have the potential to delay pathogen-induced tumorigenesis." (PMID 31681283, 2019). "The time course of BEC infected with S. aureus showed that the phosphorylation of GSK3α (Ser21) and GSK3β (Ser9) increased significantly after 40 min of infection, GSK3α phosphorylation (~8-fold compared with control) being higher than GSK3β (~2.5-fold compared with control)." (PMID 29434603, 2018). "While infection of NRVMs with Ad.myr-Akt caused the expected increase in phosphorylated GSK3β, incubation with either 5377051 or 6410136 failed to significantly inhibit Akt activity even at concentrations of 50 μM." (PMID 28336914, 2017). "However, infection of the heterophils with S. Enteritidis significantly (p ≤ 0.05) increased phosphorylated GSK-3β (Ser9) within 30 min." (PMID 26664916, 2014). "The phosphorylation of Ser9 was detectable after infection with both IAV strains from 6 h p.i. and lasted at least up to 10 h p.i., thus, showing that infection of cells with influenza viruses results in inactivation of GSK-3β and assuming an accumulation of endogenous β-catenin within the cell." (PMID 24767605, 2014). "Second, the antibody array provides data that PI3K/Akt signaling inactivates (phosphorylates) GSK-3β to allow the enhanced NF-κB activity resulting in the increased expression of pro-inflammatory cytokines in heterophils following infection with S. Enteritidis." (PMID 26664916, 2014). "However the basal level of expression of the proteins like Akt, GSK3β, Ras, mTOR, 4EBP1 and S6K remain unchanged during infection as well as in presence of GA." (PMID 24959709, 2014). "In the setting of murine CM (ECM), we demonstrate that infection results in aberrant cerebral regulation of Akt/GSK3β signaling, a change that may result in abnormal cognitive function and long-term neurological sequelae." (PMID 23082110, 2012). "We found a reduced GSK-3β phosphorylation by the Sterne infection in comparison with dSterne." (PMID 19416348, 2009). "Furthermore, infection with some viruses (e.g., human T-cell leukemia virus type 1 [HTLV-1]) causes increased levels of GSK3β phosphorylation and decreased levels of proinflammatory cytokines tumor necrosis factor alpha (TNF-α), IL-8, and monocyte chemotactic protein 1 (MCP-1)." (PMID 36995259, 2023). "Future studies that demonstrate a participation of cellular proteins such as GSK3β inviral infections may allow potential use as a specific therapeutic target for thetreatment of infections, capitalising on participation of the kinase in later stepsof the signalling pathway." (PMID 32130369, 2020). "Therefore, the regulation of GSK3B may protect host cells from H. pylori’s infection, making GSK3B a therapeutic target for the prevention of H. pylori-driven gastric disorder." (PMID 30687082, 2018). "To further confirm the role of GSK-3β in inhibiting the nuclear translocation of NRF2, we transfected macrophages with constitutively active (CA)-GSK-3β construct followed by infection at an 8 h time point." (PMID 41277868, 2026). "Pretreatment with H-89 markedly reduced p-GSK-3βSer9 protein level at 8 h post-infection compared to the infected control (54.8% decrease compared with infected control, P = 0.0006), implying the role of PKA in inhibiting GSK-3β activity." (PMID 41277868, 2026).
infection (continued). "Mechanistic studies show that C. atrati extracts and purified 4′HAP exert strong anti-parasitic effects by selectively activating GSK3β, which in turn destabilizes HIF-1α under infection conditions." (PMID 41509906, 2026). "Treatment with 25 mg/kg–50 mg/kg of baicalin raised the protein levels of GSK-3β and β-catenin and inhibited the protein levels of WNT3A and c-Myc compared to the infection group (p < 0.05)." (PMID 40427615, 2025). "CRISPR inactivation of either GSK3α or GSK3β independently in THP-1 cells (left group) confirmed these findings, showing about 50% and 30% reduction of intracellular Mtb 72 h post infection, respectively." (PMID 39175770, 2024). "Genetic validation using gene silencing and CRISPR knockout of both GSK3α and GSK3β in THP-1 cells, demonstrate the role of both genes in controlling early infection of Mtb in these monocytic like macrophages." (PMID 39175770, 2024). "The GSK-3β inhibitor lithium, which is utilized as a treatment for psychiatric disorders such as SCZ and BPD, has been shown to inhibit infection by several viruses, including coronaviruses." (PMID 35444632, 2022). "Following infection with a KOS HSV-1 strain with an MOI of 0.1, a significant increase in phosphorylation of GSK-3β was observed in the wild-type cells." (PMID 34749529, 2021). "GSK3β participation in the DENV-2 replication process was evaluated withpharmacological and genetic inhibition during early [0-12 h post-infection(hpi)], late (12-24 hpi), and 24 hpi in Huh7 and Vero cells." (PMID 32130369, 2020). "Considering that PI3K/Akt kinase pathway is involved in the infection of epithelialcells, Huh-7 and Vero, by DENV-211 and that GSK3β is downstream of this cascade, it is intriguing to evaluate therole of GSK3β in the infective process of DENV-2." (PMID 32130369, 2020). "Infection by HSV-1 alters neuronal gene expression for neprilysin and modulates enzyme activity for neprilysin and GSK3β—key enzymes involved in Aβ deposition and hyperphosphorylation of tau protein." (PMID 29559905, 2018). "We examined the inactive phosphorylated state of glycogen synthase kinase-3 beta (p-GSK3β) over 120 h P. gingivalis infection and found p-GSK3β, an important EMT regulator, significantly increases over the course of infection (p < 0.01)." (PMID 29250491, 2017). "A. actinomycetemcomitans CDT rapidly decreases phospho-Akt and phospho-GSK-3β in infected macrophages while C. jejuni CDT would not be a critical factor for the activation of PI3K/Akt pathway during infection." (PMID 28713773, 2017). "By 60 min after infection, the amount of total GSK-3β was reversed where significantly (p ≤ 0.05) more total GSK-3β was found in the infected heterophils compared to the uninfected control cells." (PMID 26664916, 2014). "Using a specific GSK-3β ELISA assay, 30 min after infection with S. Enteritidis, heterophils had a significant decrease (p ≤ 0.05) in total GSK-3β, but a significant increase (p ≤ 0.05) in phosphorylated GSK-3β (Ser9)." (PMID 26664916, 2014). "At 24 hr post-infection, transduced BMVEC were lysed and examined for over-expression of the mutant protein as indicated by higher levels of GSK3β and the hemagglutinin (HA) tag which is only present on the transgene." (PMID 23418486, 2013). "We therefore checked the time kinetics (0–24 h) of GSK-3β and found no such significant difference in the protein level expression during infection." (PMID 41277868, 2026). "On the other hand, PKA-mediated glycogen synthase kinase-3 beta (GSK-3β) phosphorylation at the Ser-9 position rendered it inactive and removed its inhibitory effect on NRF2, thus allowing its nuclear translocation during infection." (PMID 41277868, 2026). "The 25 to 100 mg/kg of baicalin could enhance GSK-3β and β-catenin mRNA expressions and attenuate WNT3A and c-Myc mNRA expression levels compared to the infection group (p < 0.01)." (PMID 40427615, 2025).
infection (continued). "The connection between infection and AD and Tau phosphorylation is supported by evidence such as HSV-1 infection inducing Tau phosphorylation in an AD-like manner that is due to the viral stimulation of GSK-3β and PKA." (PMID 39416952, 2024). "Collectively, these data suggest that GSK3β activity is not required to drive the downregulation of megalin in our experimental setting and that under IV infection conditions, downregulation of albumin uptake is independent of GSK3β activation." (PMID 37727782, 2023). "A focused GSK3β inhibitor library provided by Takeda Pharmaceutical Company (Japan) was screened against both SARS-CoV-2 and human alpha coronavirus HCoV-229E-infected Huh-7.5.1 cells and monitored for either dsRNA or N protein levels as markers of infection." (PMID 36508083, 2022). "GSK-3α content significantly increased at 75 days of infection, but no changes were observed in GSK-3β." (PMID 34303703, 2021). "Inhibiting GSK3β did not affectviral titres or the amount of intracellular DENV E protein in pre-treated cells or at early infection (0-12hpi)." (PMID 32130369, 2020). "The inactivation of GSK3β would explain the lack of effect on virusproduction upon chemical inhibition of GSK3β at this stage of infection." (PMID 32130369, 2020). "Infected animals, which underwent no further treatment showed enhanced signaling of GSK-3β and decreased Beta-catenin in comparison with the uninfected control, indicating decreased activity of the canonical Wnt-pathway due to infection." (PMID 32424558, 2020). "Neithertreatment with GSK3β inhibitor at early infection stages 0-12 hpi nor at late infection stages 12-24 hpi, had significant effects on DENVE distribution pattern." (PMID 32130369, 2020). "Interestingly, pathways active during infection including PI3K-AKT and Wnt signaling both converge at the inactivation of GSK3β, indicating redundant mechanisms in place to ensure the different outcomes that are mediated by inhibition of the kinase." (PMID 31681283, 2019). "Further testing the activity of GSK-3β in the GAS-infected RAW264.7 cells revealed that a reduction of GSK-3β serine 9 phosphorylation, which was an indication of GSK-3β inactivation, was observed both in the wild type GAS- and the sagB mutant-infected RAW264.7 cells at 3 h post-infection." (PMID 30926881, 2019). "Louis, MO, USA) led a robust phosphorylated GSK3β and a moderately increased expression of TLR4 and MyD88 proteins but reduced the abundance of NF-κB and GSK3β proteins in U937-derived macrophage-like cells in response to the H37Rv infection." (PMID 30356420, 2018). "Given the interactions between GRA18 and β-catenin, GSK3β, and PP2A-B56, we hypothesized that GRA18 could interfere with β-catenin regulation in the course of infection." (PMID 30320549, 2018). "The β-catenin expression level in HUVECs treated with GSK-3β knockdown under no-infection conditions was 76 % of those without knockdown treatment (P = 0.0126)." (PMID 25385175, 2015). "Under no-infection conditions, GSK-3β knockdown treatment resulted in suppression of GSK-3β expression in HUVEC to about 20 % of the level without treatment." (PMID 25385175, 2015). "The total amount of GSK-3β in IAV PR8-infected cells was only slightly decreased to 83 % of the no-infection control cells, and the decrease was not significant (P = 0.3553)." (PMID 25385175, 2015). "In line with our hypothesis, infection with ExoT or ExoT/ADPRT-expressing strains (∆U and ∆U/T(G-A+) respectively) reduced Akt activation (p-AktS473) levels by 6hr and p-Akt-mediated GSK-3β phosphorylation (inactivation) by 8hr post-infection." (PMID 26020630, 2015). "This was associated with general group effects on the mean protein expression of total GSK3β (p<0.05), although there were no specific effects of infection condition when comparing the different treatment groups by Tukey's multiple comparison test." (PMID 23082110, 2012).